S100A13 (S100 calcium binding protein A13)
Diseases named in the same sentence as S100A13 in open-access papers (continued):
Sharing a sentence is not in itself a finding about the gene and the disease.
non-small cell lung carcinoma (3 papers, 2021 to 2024). A group of at least three distinct histological types of lung cancer, including non-small cell squamous cell carcinoma, adenocarcinoma, and large cell carcinoma. "Miao et al25 reported that elevated S100A13 level is linked to tumor angiogenesis in patients in the early-stage of non-small cell lung cancer, leading to poor prognosis." (PMID 39128058, 2024). "S100A13’s overexpression was associated with intratumoral angiogenesis and more aggressive invasive phenotype in non-small-cell lung cancer." (PMID 34262872, 2021).
pancreatic cancer (3 papers, 2021 to 2023). "S100A13/P were significantly upregulated in pancreatic carcinoma, with fold changes of 2.68 and 17.73 in Segara’s dataset." (PMID 34804125, 2021). "Indeed, a recent metadata analysis using Oncomine and GEPIA found significantly higher levels of S100A13 transcripts in pancreatic tumors than in control tissues." (PMID 37627239, 2023).
papillary thyroid carcinoma (3 papers, 2016 to 2023). "Growing evidence showed that S100A13 has a strong relationship with tumorigenesis, and it has been proved as a novel biomarker for papillary thyroid carcinomas (PTC)." (PMID 34712325, 2021). "With multiplexed and targeted mass spectrometry method, S100A13 was also found to be elevated in papillary thyroid carcinoma (PTC) compared to normal tissue, suggesting that S100A13 may be considered as a novel candidate PTC biomarker." (PMID 27008379, 2016).
astrocytoma (2 papers, 2024 to 2025). "Furthermore, the expression of S100A13 does not seem to show a strong impact on the prognosis of IDH wt GBMs or IDH mut astrocytoma." (PMID 39744679, 2025).
diabetic retinopathy (2 papers, 2020 to 2024). "When examining the methylation status in chronic T2DM with and without diabetic retinopathy compared to T2DM with shorter disease duration, differential methylation of S100A13 was found in diabetic retinopathy, and S100A13 was identified as a possible biomarker." (PMID 39123454, 2024).
Hyperglycemia (2 papers, 2020 to 2022). An increased concentration of glucose in the blood. "We speculate that significant demethylation of S100A13 in individuals with DR downregulates S100A13 and upregulates p38 MAPK and nuclear factor-kappa B through calcium signaling and the RAGE pathway, thus increasing the damage caused by hyperglycemia." (PMID 32493412, 2020).
asthma (1 paper, 2023). "We found that CLC and S100A13 were among the top genes showing differential expression in airway epithelium in asthma." (PMID 36793728, 2023).
astroglioma (1 paper, 2022). "One study investigated the relationship between the expression of S100A13 in human astroglioma in relation to tumor grade and vascularization, which results indicated that S100A13 is overexpressed in human high grade astrocytic gliomas and correlates with tumor grading and microvessel density." (PMID 36046652, 2022).
bladder cancer (1 paper, 2022). "Low expression of lncRNA LINC00665 inhibits the invasion and proliferation of bladder cancer by regulating S100A13." (PMID 35812753, 2022).
cyst (1 paper, 2015). A sac-like closed membranous structure that may be empty or contain fluid or amorphous material. "Western blot analyses showed expression of expected protein products for CK-19, ANXA3, CMBL and S100A13 in cyst fluids." (PMID 25978681, 2015). "To further evaluate our findings, we performed ROC curve analyses and determined that the concentration >230 pg/ml was the optimal cut-off for S100A13 in cyst fluid for discrimination of cPTC from benign thyroid cysts by ELISA." (PMID 25978681, 2015). "WB analyses of cyst fluid and IHC on corresponding tissue samples confirmed a significant up-regulation of cytokeratin 19 (CK-19/CYFRA 21-1) and S100A13 in cPTC vs. benign lesions." (PMID 25978681, 2015). "Based on the results from IHC and Western blot analyses, CK-19 and S100A13 were further analyzed by ELISA in non-depleted cyst fluid samples of the extended material of 17 cPTCs and 55 benign cystic lesions as well as reference samples." (PMID 25978681, 2015). "Further evaluation of CK-19, S100A13 and VIM was performed by ELISA using non-depleted cyst fluid from the extended material of cPTC and benign cystic thyroid lesions as well as cystic reference cases." (PMID 25978681, 2015).
eosinophilia (1 paper, 2015). "The promoter region of S100A13 was hypomethylated in patients with anticipated and known clonal eosinophilia." (PMID 26497854, 2015).
hepatocellular carcinoma (1 paper, 2022). A malignant tumor that arises from hepatocytes. "In addition, compared to para-cancer tissues, S100A13 was expressed at higher levels in hepatocellular carcinoma (HCC) tissues, and higher mRNA expressions of S100A13 was shown to have shorter overall survival." (PMID 35300639, 2022).
metastatic cancer (1 paper, 2016). A carcinoma which has spread from the original site of growth to another anatomic site. "Moreover, S100A13 was detected in tumor cells circulating in blood of patients with metastatic cancer, indicating that S100A13 could be considered as a predictor of metastases." (PMID 27008379, 2016).
osteoporosis (1 paper, 2025). A condition of reduced bone mass, with decreased cortical thickness and a decrease in the number and size of the trabeculae of cancellous bone (but normal chemical composition), resulting in increased fracture incidence. "In patients suffering with osteoporosis, SPARCL1-OC followed by HSP1IA-OC parathyroid oxyphil cells were highly clustered, while in non-osteoporosis patients CXCL10-PCC followed by S100A13-PCC parathyroid chief cells were highly clustered." (PMID 40496565, 2025).
pancreatic ductal adenocarcinoma (1 paper, 2021). An infiltrating adenocarcinoma that arises from the epithelial cells of the pancreas. "Higher expressed S100A13/16/P were found in pancreatic ductal adenocarcinoma (fold change = 2.19, 2.33, 13.18) of Badea’s datasets." (PMID 34804125, 2021).
psoriasis (1 paper, 2022). An autoimmune condition characterized by red, well-delineated plaques with silvery scales that are usually on the extensor surfaces and scalp. "The strong link between ELOVL4 and IL36B, CDK7, CHMP2B, and S100A13 was also evident in RNA-Seq data sets of psoriasis lesional skin." (PMID 35900871, 2022).
thyroid tumor (1 paper, 2016). A benign or malignant neoplasm affecting the thyroid gland. "The immunohistochemistry analysis showed that S100A13 was stained in 94.3 % of thyroid tumors, predominantly in nuclear with faint cytoplasmic staining, and was stained in 60.0 % in normal thyroid tissue (P = 0.007)." (PMID 27008379, 2016).
tumor (30 papers, 2008 to 2026). "Overexpression of S100A13 protein is associated with tumor angiogenesis, and poor survival in patients with early-stage NSCLC." (PMID 35584089, 2022). "High S100A13 level is strongly associated with tumor angiogenesis and poor prognosis." (PMID 34917619, 2021). "Although implicated in many biological processes, such as export of FGF1 and IL1‐α and tumour angiogenesis, the exact function of S100A13 in skeletal muscle remains elusive." (PMID 41582615, 2026). "S100 family members such as S100A8, S100A9, S100A13, and S100A6 are upregulated in advanced BC and are associated with tumor progression, immune suppression, and poor prognosis." (PMID 41404073, 2025). "In the case of GBM, we observed relatively high expression of S100A13 in myeloid cells located at the tumor's leading edge." (PMID 39744679, 2025). "In line with the earlier findings, UVM tissue had much higher S100A13 protein levels than adjacent non-tumor tissues." (PMID 36793711, 2023). "The abnormal regulation of S100 proteins, including S100A13, is related to tumor cell proliferation, immune infiltration, and change of chemosensitivity." (PMID 37583433, 2023). "The gene expression profile analysis demonstrated that the levels of S100A4/S100A6/S100A10/S100A11/S100A13/S100P were higher in tumor than in normal liver samples." (PMID 33815482, 2021). "S100A13 was found overexpressed in tumours of PTC origin (log2fc = 1.03, p < 0.05) compared to normal thyroid." (PMID 25880590, 2015). "The role of S100A13 and CK-19 proteins should be evaluated in prospective studies on independent tumor material using FNAB samples taken preoperatively." (PMID 25978681, 2015). "Analysis of four publicly available gene expression datasets, three of them comparing matched normal-PTC tumour samples, confirmed the overexpression of S100A13 mRNA transcripts in PTC." (PMID 25880590, 2015). "The analysis revealed that in the training set, the expression of BANF1, CDK2AP2, DDT, LRIG1, MRPL4, and S100A13 was significantly upregulated in tumor samples, and the expression of EPS8, NUCB2, PAF1, PMP22, RABGAP1L, and USO1 was higher in control samples (p < 0.05)." (PMID 41000388, 2025). "Our findings suggest that S100A13 may potentially have tumor suppressive function at an early stage of cancer development." (PMID 30670674, 2019). "The study on the involvement of S100A13 in the development of GBM revealed that the cells expressing this gene were located in peripheral and infiltrating areas of the tumor." (PMID 39744679, 2025). "According to the studies, we found that the upregulation of CRISP3, S100A13, and S100A16 in domain 3 suggests that this region possesses tumor invasiveness, metastatic potential, and an active inflammatory environment, thereby promoting tumor progression." (PMID 41223185, 2025). "A decreased protein level in PDAC+ DM compared to PDAC was also detected via Western blots, which indicates a lower influence of S100A13 on tumor angiogenesis in these PDAC patients, rendering S100A13 an interesting marker for patients with PDAC+ DM." (PMID 39123454, 2024). "In order to identify the representative S100A13 protein levels in UVM tissue and adjacent non-tumor tissues acquired from patients being treated at the Eye Center of Xiangya Hospital, immunohistochemistry (IHC) labeling was performed." (PMID 36793711, 2023). "One more S100A member, S100A13, facilitated the release of FGF1 under heat shock conditions, modulating the proliferation of tumor endothelial cells synergistically effect with VEGF-A." (PMID 34209679, 2021). "Compared with para-cancer tissues, the expression levels of S100A4/S100A6/S100A10/S100A11/S100A13/S100A14/S100P were higher in HCC tissues, while the expression levels of S100A8/S100A9/S100A12 were decreased in tumor tissues." (PMID 33815482, 2021).
tumor (continued). "S100A13 can act on the regulation of FGF-1 and participate in the regulation of VEGF-A, which is related to tumor grading and promotes tumor to be more invasive and aggressive." (PMID 33046974, 2020). "The tissue microarray was performed to investigate the correlation between S100A13 and HMGA1 expression in tumor tissues." (PMID 27008379, 2016). "In contrast, several S100 genes had similar expression levels across multiple tumour types, including S100A14, S100A13 and S100A3." (PMID 18781180, 2008). "Endothelial cells exposed to S100A13 and S100A6 display increased angiogenic activity through VEGF and ERK pathway activation, linking S100 signaling to neovascularization and nutrient supply within the tumor." (PMID 41404073, 2025). "Specific members such as S100C, S100A8, S100A9, and S100A13 exhibit distinct expression patterns in non-muscle-invasive and muscle-invasive disease, with functional implications for tumor behavior." (PMID 41404073, 2025). "However, a correlation was found between the transcript levels of S100A13 and S100A11 (R = 0.67), in the tumor array." (PMID 37627239, 2023). "In addition, correlations were also noted in the tumor array between S100A11 and S100A2 (R = 0.54), S100A4 (R = 0.46), S100A6 (R = 0.49), S100A13 (R = 0.67), S100A14 (R = 0.65), and S100A16 (R = 0.78)." (PMID 37627239, 2023). "S100A13 protein was present in significantly higher level in pretreatment tumor DTIC/TMZ non-responder versus responder group." (PMID 37182181, 2023). "While other members of this family, such as S100A4, S100A7 and S100A13, have been shown to participate under similar conditions, this discussion focuses on S100A8/A9's role in tumorigenesis by reviewing the effects of S100A8/A9 on tumor cells or vascular endothelial cells." (PMID 22685372, 2012).
cancer (14 papers, 2015 to 2024). A tumor composed of atypical neoplastic, often pleomorphic cells that invade other tissues. "In particular, for THCA the model involves S100A13, a gene encoding a calcium binding protein that has been proposed to be a new marker of angiogenesis in various cancer types." (PMID 25578962, 2015). "S100A13 has also been implicated in the regulation of some cancer." (PMID 30670674, 2019). "The levels of S100A13 transcripts were higher in the control HPNE cell line (Ct = 4.78 +/− 1.33) than in the cancer cell lines." (PMID 37627239, 2023). "For S100A13, based on the current literature, we anticipated observing lower levels of S100A13 in HPNE cells than in cancer cells." (PMID 37627239, 2023). "Based on the Oncomine database, there are no obvious distinctions in S100A1, S100A4, S100A5, S100A6, and S100A13 expressions between cancer tissues and normal colon mucosa, and S100A7, S100A12, and S100Z are slightly overexpressed in CRC tissues." (PMID 33294444, 2020). "S100A13 is a novel member of S100 family that characterized by its specificity in various form of cancer." (PMID 30558666, 2018). "It was reported that the IL1α-S100A13 complex plays an important role in cell proliferation and angiogenesis, and would be an effective strategy to inhibit a wide range of cancers." (PMID 27008379, 2016). "Increasing evidences also showed the association between S100A13 and tumourigenesis, indicating the role of S100A13 in initial and progression in diversity of cancer." (PMID 27008379, 2016). "Interestingly, inhibition of the IL1alpha-S100A13 complex has been suggested to be an effective strategy to inhibit uncontrolled cell division of a broad range of different cancer types." (PMID 26497854, 2015). "S100A13 and high mobility group A (HMGA1) are knownto play essential roles in the carcinogenesis and progression of cancer." (PMID 27008379, 2016). "Moreover, S100A13 overexpression promotes oncogene Ras-induced cell senescence (Ras OIS), Doxorubicin-induced cancer cell senescence (TIS) and replicative senescence, while impairment of non-classical secretory pathway of IL-1α delays cellular senescence." (PMID 30670674, 2019). "Although for most S100s, and for HMGB1, the transcript levels were lower in the control HPNE cells than in the cancer cell lines, this was not the case for S100A4, S100A6, S100A7, S100A12, and S100A13." (PMID 37627239, 2023). "However, the correlation between S100A13 and HMGA1 during cancer progression is not yet well understood." (PMID 27008379, 2016).
S100A13 also shares sentences with these, for which no sentence is quoted: adenomyosis (1 paper); alcohol abuse (1); Alzheimer disease (1); anemia (1); Atherosclerotic lesion (1); Cachexia (1); colorectal cancer (1); Cutaneous Malignant Melanoma (1); diabetes mellitus (1); endometrioid ovarian cancer (1); Hypertension (1); low grade glioma (1); Obesity (1); ovarian endometriosis (1); pancreatic adenocarcinoma (1); proliferative diabetic retinopathy (1); prostate carcinoma (1); schizophrenia (1); serous ovarian cancers (1); type 2 diabetes (1).